ENSG00000221245
Synonyms: LOC124900187
Gene: Small nucleolar RNA gene on chromosome 4 (119,569,699 to 119,569,825, forward strand). Ensembl gene ENSG00000221245.
Gene Ontology:
Biological process: RNA processing
Cellular component: nucleolus
Homologues: Orthologues: rat LOC120102095 (74% identical), mouse Gm22676 (72% identical). Paralogues in human: SNORA11F (85% identical), SNORA11B (84% identical), SNORA11C (84% identical), SNORA11D (84% identical), SNORA11E (84% identical), SNORA11 (83% identical), SNORA11G (72% identical).